PHF8 (PHD finger protein 8)
Diseases named in the same sentence as PHF8 in open-access papers (continued):
Sharing a sentence is not in itself a finding about the gene and the disease.
colorectal tumor (1 paper, 2023). "In this study, we functionally validate the relationship between tumoral PHF8 and anti-tumor immunity in multiple colorectal tumor models." (PMID 37454216, 2023). "In spite of an immune-suppressive role of PHF8 in colorectal tumor-bearing models, it is critical to dissect how PHF8 impairs tumor immunity." (PMID 37454216, 2023). "Ablation of PHF8 function in colorectal tumor cells induces the expression of a cluster of transposable elements and releases immunostimulatory nucleic acids, ultimately leading to the activation of interferon signaling and antigen processing and presentation." (PMID 37454216, 2023). "Furthermore, PHF8 mRNA levels negatively correlated with IFNG, TLR3, IFIH1, STAT1 and OASL expression, suggesting that PHF8 restrains adaptive immune responses in human colorectal tumors." (PMID 37454216, 2023). "Overall, our findings identify the underlying mechanism by which PHF8 decreases colorectal tumor immunogenicity and suggest that targeting PHF8 is a promising viral mimicry-inducing approach to enhance intrinsic anti-tumor immunity and further obliterate colorectal tumor growth." (PMID 37454216, 2023). "We also tested these results in a series of human colorectal tumor cell lines using the CCLE database and Mendeley Data40, and consistently found that PHF8 expression was negatively correlated with human ERV expression." (PMID 37454216, 2023). "Given that PHF8 depletion activated human ERV expression and subsequent antiviral responses in murine and human colorectal tumor cells, we further explored the correlation of PHF8 expression and antiviral responses using RNA-seq data derived from the TCGA database." (PMID 37454216, 2023).
deafness (1 paper, 2020). An inherited or acquired condition characterized by the complete loss of the ability to hear from one or both ears. "Additional studies are required to develop more in-depth insights into the molecular mechanisms and elucidating the role of PHF8 in organogenesis and deafness in the future." (PMID 33330448, 2020).
endothelial dysfunction (1 paper, 2025). In vascular diseases, endothelial dysfunction is a systemic pathological state of the endothelium (the inner lining of blood vessels) and can be broadly defined as an imbalance between vasodilating and vasoconstricting substances produced by (or acting on) the endothelium. "Similar changes in the expression of miR-22-3p, Phf8, mTOR- and autophagy-related proteins/mRNAs were also found in vivo in hearts of severely HHcy Cbs−/− mice, which show endothelial dysfunction." (PMID 39859460, 2025).
esophageal squamous cell carcinoma (1 paper, 2013). Esophageal squamous cell carcinoma (ESCC) is a type of esophageal carcinoma (EC) that can affect any part of the esophagus, but is usually located in the upper or middle third. "We therefore hypothesized that PHF8 may have important effects on tumorigenesis in esophageal squamous cell carcinoma (ESCC)." (PMID 24146981, 2013). "Here, we studied the role of one of the histone lysine demethylases, plant homeodomain finger protein 8 (PHF8), in the carcinogenesis of esophageal squamous cell carcinoma (ESCC)." (PMID 24146981, 2013).
Ewing sarcoma (1 paper, 2016). A small round cell tumor that lacks morphologic, immunohistochemical, and electron microscopic evidence of neuroectodermal differentiation. "Since, miR-22 was reported to target and regulate KDM3A in Ewing sarcoma, these findings suggest that miR-22 may regulate both PHF8 and KDM3A in LNCaP cells, at steady state as well as in the presence of CS-FBS or IL-6." (PMID 27689328, 2016).
gallbladder carcinoma (1 paper, 2023). "Therefore, this study evaluated the expression patterns and the association of PAK4 and PHF8 in human gallbladder carcinomas (GBCs) and assessed the prognostic significance of their expression patterns." (PMID 36980457, 2023). "Multivariate analysis showed that nuclear PAK4 expression and nuclear PHF8 expression were independent predictors of overall survival and relapse-free survival in gallbladder carcinomas." (PMID 36980457, 2023). "Furthermore, coexpression of nuclear PAK4 and nuclear PHF8 predicted shorter overall survival (p < 0.001) and relapse-free survival (p < 0.001) of gallbladder carcinoma in multivariate analysis." (PMID 36980457, 2023). "However, despite extensive studies in human cancers, there are limited reports on the roles of PAK4 and PHF8 in gallbladder cancers." (PMID 36980457, 2023). "Although it has been reported that PAK4 is overexpressed in gallbladder cancer during the evaluation of gene expression profiles of gallbladder cancers, studies on PAK4 and PHF8 in gallbladder cancer have been limited." (PMID 36980457, 2023). "Moreover, considering that PAK4 shows its kinase activity upon interaction with CDC42 and CDC42 signaling is regulated by PHF8, there might be potential relationships between the roles of PAK4 and PHF8 in the progression of gallbladder cancers." (PMID 36980457, 2023).
hypopharyngeal carcinoma (1 paper, 2022). Carcinoma, predominantly squamous cell, arising from the epithelial cells of the hypopharynx. "Finally, the high expression of PHF8 was associated with clinical stage, shorter overall and disease-free survival, and tumor relapse in laryngeal and hypopharyngeal carcinomas." (PMID 35326475, 2022). "The upregulation of PHF8 was observed in laryngeal and hypopharyngeal carcinomas." (PMID 35326475, 2022).
metastatic melanoma (1 paper, 2022). A melanoma that has spread from its primary site to another anatomic site. "PHF8 is up-regulated in metastatic melanoma and promotes invasion via transcriptional activation of TGFβ pathway genes." (PMID 35179962, 2022). "Primary cell lines displayed variable levels, whereas most metastatic melanoma cell lines expressed high PHF8 levels." (PMID 35179962, 2022).
osteoporosis (1 paper, 2022). A condition of reduced bone mass, with decreased cortical thickness and a decrease in the number and size of the trabeculae of cancellous bone (but normal chemical composition), resulting in increased fracture incidence. "In summary, we first found that decreased PHF8 expression deturbed osteogenic differentiation of BMSCs and inhibited the Wnt/β-catenin signaling pathway in osteoporosis rats." (PMID 36518887, 2022). "Then this study identified a new target, PHF8, regulating BMSC osteogenic differentiation, providing crucial insight into the mechanism underlying the pathogenesis of osteoporosis and new therapeutic options for osteoporosis." (PMID 36518887, 2022). "Using an animal model of osteoporosis and in vitro BMSCs culture, we examined the expression of PHF8 and the osteogenesis efficiency of BMSC." (PMID 36518887, 2022). "Collectively, our data revealed that the decreased expression of PHF8 in osteoporosis rats suppressed the osteogenic differentiation of BMSCs, which was then restored by PHF8 overexpression." (PMID 36518887, 2022). "Here, we identified that PHF8 played a protective role in osteoporosis by affecting osteogenic differentiation via the Wnt/β-catenin signaling pathway." (PMID 36518887, 2022). "Furthermore, the protein level of PHF8 was downregulated in the OVX group in comparison to the sham group, which suggested that PHF8 played a role in the osteoporosis of rat." (PMID 36518887, 2022). "In this study, we aimed to explore the role of PHF8 in osteoporosis." (PMID 36518887, 2022). "We found that overexpression of PHF8 in rBMSC promoted osteogenic differentiation, suggesting that PHF8 might play a role in osteoporosis by regulating rBMSC osteogenic differentiation." (PMID 36518887, 2022). "In this study, we found a reduction of PHF8 expression in osteoporosis rats." (PMID 36518887, 2022). "The results showed that PHF8 expression was decreased in osteoporosis rats compared to controls." (PMID 36518887, 2022). "In addition, the Wnt/β-catenin signaling pathway in BMSCs was inhibited in osteoporosis rats, which was rescued by overexpression of PHF8." (PMID 36518887, 2022). "Therefore, PHF8 plays a role in the osteogenic differentiation of BMSCs via the Wnt/β-catenin signaling pathway and could be a potential therapeutic target for osteoporosis." (PMID 36518887, 2022).
Parkinson disease (1 paper, 2023). A progressive degenerative disorder of the central nervous system characterized by loss of dopamine producing neurons in the substantia nigra and the presence of Lewy bodies in the substantia nigra and locus coeruleus. "As alpha-synuclein (SNCA), a critical protein in Parkinson’s disease pathogenesis, turned out to be amongst the main proteins identified via proteomics to be downregulated by PHF8 depletion." (PMID 36831023, 2023). "Here we investigate the function of such an enzyme: PHF8 is a histone demethylase that has been implicated in two conditions: the first being X-linked intellectual disability (XLMR), a condition characterized by a profound loss of memory formation, and the second being Parkinson’s disease." (PMID 36831023, 2023).
Partington syndrome (1 paper, 2021). A rare neurological condition that is primarily characterized by mild to moderate intellectual disability and dystonia of the hands. "Collectively, these findings suggest that PHF8 and ZNF711 may act as gene modifiers of ARX-disease phenotypes; thus, variants in these NDD genes may contribute to the phenotype variability from West syndrome to Partington syndrome to mild ID caused by ARX polyalanine expansions." (PMID 34356104, 2021).
prostate tumors (1 paper, 2016). "In prostate tumors from these mice (N=7), PHF8 expression was detectable at the stage of atypical hyperplasia and in well differentiated tumors, but was low or non-detectable in the poorly differentiated tumors." (PMID 27689328, 2016). "Next, we investigated PHF8 expression in normal prostate and prostate tumors from the TRAMP mouse, an animal model that has been widely used for PCa studies." (PMID 27689328, 2016). "In sum, PHF8 and AR were confirmed to be co-expressed in human PCa samples, mouse prostate, and mouse prostate tumors, supporting our cell line-based findings that AR positively regulates PHF8." (PMID 27689328, 2016).
rheumatoid arthritis (1 paper, 2025). A chronic, systemic autoimmune disorder characterized by inflammation in the synovial membranes and articular surfaces. "Here, we identify auranofin, the FDA-approved drug for rheumatoid arthritis, as a lead compound capable of binding to the BRCT 7–8 domains and blocking TOPBP1 interaction with PHF8 and FANCJ." (PMID 41392982, 2025). "In this study, we identified auranofin, an FDA-approved anti–rheumatoid arthritis agent, as a TOPBP1 inhibitor with high potency in disrupting the interaction of TOPBP1 with PHF8 and FANCJ by docking to the hydrophobic pocket of BRCT 7–8." (PMID 41392982, 2025).
schizophrenia (1 paper, 2022). A major psychotic disorder characterized by abnormalities in the perception or expression of reality. "PHF8, SAP30 and KDM5B as co regulators of the three hub genes may provide a new idea for the treatment of schizophrenia." (PMID 36421842, 2022).
Siderius-Hamel syndrome (1 paper, 2026). "To investigate this, we examine in neural stem cells the role of PHF8, a histone demethylase whose mutations are linked to Siderius-Hamel syndrome, a rare neurodevelopmental disorder." (PMID 41714361, 2026).
X-linked intellectual disability (1 paper, 2023). An X-linked intellectual deficiency in which not enough information is known, reported or published to indicate whether a gene causes non-syndromic or syndromic presentations. "Here, we used quantitative proteomics to study the role of PHD Finger Protein 8 (PHF8), a histone demethylating enzyme found to be mutated in X-linked intellectual disability and identified as a genetic marker of PD, in regulating the expression of PD-related synaptic plasticity proteins." (PMID 36831023, 2023).
cancer (30 papers, 2013 to 2025). A tumor composed of atypical neoplastic, often pleomorphic cells that invade other tissues. "PHF8 has been implicated in various types of human cancers, including BC, where it contributes to tumor progression by regulating cell cycle progression, DNA damage response, and oncogenic expression." (PMID 41198671, 2025). "PHF8 has also been implicated in tumor immune responses and its association with interleukin-6 (IL-6) has been validated in a number of cancer types." (PMID 39311138, 2024). "The underlying molecular mechanisms of PHF8 in cancer biology have been gradually discovered in specific tumor contexts." (PMID 37454216, 2023). "PHF8 has been described as an oncoprotein that is positively associated with aggressive clinical features, poor prognosis and relapse of cancers." (PMID 30180906, 2018). "In this study, we found that PHF8 loss in tumor cells removes an epigenetic checkpoint that restrains antiviral immune responses, endogenous nucleic acid sensing and tumor inflammation, leading to an effective immune response against cancer cells." (PMID 37454216, 2023). "The prognostic impact of the expression of PAK4 and PHF8 might be associated with their role in cancer progression." (PMID 36980457, 2023). "PHF8 is highly expressed and associated with cancer progression and metastasis of diverse cancers." (PMID 36699616, 2022). "Because MYC, PML, and PHF8 have been implicated in human cancer metastasis, we investigated whether they were involved in CCL7 upregulation in OC-MQ." (PMID 34206004, 2021). "Although TGF-β has different roles in normal and tumor cells, PHF8 dysregulation contributes to the functional transformation of TGF-β from a cell suppressor to a pro-cancer agent in cancer cells." (PMID 39311138, 2024). "Third, how PHF8 regulates chromatic dynamics, except for transcriptional regulation, and the expression and function of PHF8 in cancer patients require further elucidation." (PMID 39311138, 2024). "In oncogenesis, PHD finger proteins like PHF1, PHF5A, and PHF8 contribute to cancer progression by dysregulating chromatin." (PMID 38813086, 2024). "The oncogenic role of PHF8 has been reported in multiple cancers, wherein PHF8 involves various regulators, downstream effectors, and signaling cascades." (PMID 39311138, 2024). "The diverse involvement of PHF8 in pathologic disorders, especially nervous system diseases and cancer, prompts us to evaluate its candidacy as a therapeutic target through the manipulation of its demethylase activity." (PMID 39311138, 2024). "Retrotransposon that gained accessibility in Phf8 KO CT26 cells were enriched for motifs recognized by TEAD, Jun-AP1, RUNX, NF-E2, and Bach, which are crucial regulators in cancer progression, cancer-associated stress responses and genome topology." (PMID 37454216, 2023). "In cancer cells, PHF8 acts as a demethylase removing methyl groups from histone proteins and, thus, altering the expression of genes involved in tumorigenesis and acting as a transcriptional coactivator of oncogenes." (PMID 36980457, 2023). "Many published works have highlighted the vital role of H4M in various cancers, and for instance, PHF8 played an oncogene function and contributed to EMT and metastasis in HCC." (PMID 36932439, 2023). "Both PAK4 and PHF8 have roles in the regulation of various cellular processes that are involved in cancer progression, including cell proliferation, survival from apoptosis, migration, angiogenesis, metabolic regulation, and immune evasion of cancer cells." (PMID 36980457, 2023). "Overall, our findings provide important evidence for harnessing epigenetic modulators such as PHF8 for cancer immunotherapy through a mechanism of viral mimicry responses." (PMID 37454216, 2023). "HAUSP via its TRAF-like domain interacted with the C-terminal region of PHF8 promoting deubiquitination and stabilization of PHF8, which resulted in an upregulation of cyclin A2, a key cell cycle regulator in cancer." (PMID 35052383, 2021).
cancer (continued). "PHF8 is ubiquitously expressed to target various genes in human cancers, and capable of pro-tumor and pro-metastasis." (PMID 30180906, 2018). "Given that PHF8 is implicated in transcriptionally activating numerous genes and frequently upregulated by hypoxia, an important inducer of autophagy that could promotes tumorigenesis and metastasis of cancer cells, we speculated that abnormal PHF8 expression was correlated with autophagy." (PMID 30180906, 2018). "These remarkable features imply that the ectopic expression of PHF8 is potentially correlated with genetic and environmental disease such as human cancer." (PMID 30180906, 2018). "Now that autophagy process contributes to cancer metastasis by accelerating degradation of E-cadherin, we presumed that PHF8-driven FIP200-dependent autophagy participated in metastasis and E-cadherin attenuation." (PMID 30180906, 2018). "Our observations are consistent with previous reports in cancer cells in which depletion of PHF8 led to reduced migration and invasion of cancer cells." (PMID 26751588, 2016). "Collectively these results indicate that the levels of PHF8, HIF1α and HIF2α were all elevated in the post-castration cancer tissues." (PMID 27991916, 2016). "In line with our results, there are reports showing that knockdown of PHF8 remarkably inhibits the proliferation of HeLa cancer cells." (PMID 24146981, 2013). "We are also exploring PHF8’s broader impact on transcriptional regulation in human cancers." (PMID 41198671, 2025). "Herein, we summarize the current knowledge of PHF8 about its structure and demethylation activity and its involvement in development and human diseases, with an emphasis on nervous system disorders and cancer." (PMID 39311138, 2024). "This action suggests that PHF8’s function is intertwined with the modification of chromatin structures to regulate gene expression, emphasizing its role in the epigenetic landscape of cancer progression." (PMID 38813086, 2024). "In addition, there are various reports on the subcellular localization of PHF8 and its prognostic significance in cancer patients." (PMID 36980457, 2023). "When considering the divergent roles of PAK4 and PHF8 in cancer progression, there might be a direct or indirect association between PAK4 and PHF8." (PMID 36980457, 2023). "Similarly, in the prostate, the expression of PHF8 was higher in cancer tissues than their normal counterparts." (PMID 36980457, 2023). "Knockdown of PHF8 attenuated HER2 overexpression-induced proliferation of cancer cells." (PMID 36980457, 2023). "Therefore, based on the oncogenic roles of PAK4 and PHF8, variable strategies to inhibit them have been evaluated in various cancers." (PMID 36980457, 2023). "Similarly, there are reports indicating that PAK4 and PHF8 are expressed in both the nuclei and cytoplasm of cancer cells." (PMID 36980457, 2023). "The subcellular distribution of PAK4 and PHF8 expression in carcinoma tissue from human gallbladders differed between cases, with some cases having expression primarily in the cytoplasm, others in the nuclei, and some in both the nuclei and cytoplasm of tumor cells." (PMID 36980457, 2023). "Thus, discovering the upstream events involved in the regulation of PHF8 is important for understanding how this enzyme is stabilized and upregulated in cancer." (PMID 35052383, 2021). "One hypothesis is that the overexpression of the H4K20me1-specific demethylase PHF8, observed in many cancers including hematopoietic malignancies, could attenuate the impact of SETD8 up-regulation on histone H4K20." (PMID 34530900, 2021). "On this basis it is not surprising that also PHF8 is implicated in the development of several types of cancer." (PMID 26751588, 2016). "It has been reported that PHF8 regulates HeLa cancer cell growth via its KDM activity." (PMID 24146981, 2013).